EZH2 (enhancer of zeste 2 polycomb repressive complex 2 subunit)
Diseases named in the same sentence as EZH2 in open-access papers (continued):
Sharing a sentence is not in itself a finding about the gene and the disease.
glioma (continued). "We found that propofol activates GABAAR to increase Src expression, thereby enhancing ZDHHC5-mediated palmitoylation of EZH2 and Oct4 and promoting the self-renewal and tumor-initiating capacity of glioma stem cells (GSCs)." (PMID 35927718, 2022). "The enhancer of zeste homolog 2 (EZH2) is an H3K27 methyltransferase that is overexpressed or mutated in numerous human malignancies, such as gliomas." (PMID 36146527, 2022). "More detailed particulars are that MSC-derived exosomal miR-133b was found to target and negatively regulate EZH2 expression, and EZH2 silencing resulted in inhibited glioma cell proliferation, invasion, and migration." (PMID 36438184, 2022). "Studies have demonstrated that miR-101 negatively regulates EZH2 expression in breast cancer, prostate cancer, and glioma." (PMID 36497343, 2022). "Previous studies utilised molecular profiling as tools to investigate the role of alterations in EZH2 expression in glioma progression." (PMID 36292072, 2022). "The other study received findings that showed exosomes from MSC carrying miR-133b decreased glioma size through the Wnt/β-catenin pathway by silencing Enhancer of Zeste 2 Polycomb Repressive Complex 2 Subunit (EZH2)." (PMID 36536420, 2022). "Wang showed that EZH2 promotes aerobic glycolysis and increases the growth in glioma cells via β-catenin signaling." (PMID 36389690, 2022). "EZH2 is believed to play a tumourigenic role in gliomas by epigenetic modulation through methylated histones and the activation of downstream transcription molecules including STAT3 and GATA4." (PMID 36292072, 2022). "Our analysis observed that high EZH2 expression was significantly associated with higher tumour grades, with EZH2-positive rates of 3.7%, 29.6%, and 66.7% in WHO grade 2, 3, and 4 gliomas, respectively." (PMID 36292072, 2022). "In IDH1 R132H-negative gliomas, there was a trend toward shorter 5-year PFS (mean = 8.0 months, p = 0.001) and 5-year OS (mean = 28.7 months, p = 0.06) in gliomas demonstrating high EZH2 expression compared with those having low EZH2 expression." (PMID 36292072, 2022). "Another group demonstrated that miR-1297 inhibited in vitro glioma cell invasion, migration and proliferation through targeting EZH2." (PMID 36183123, 2022). "TCGA datasets also indicate that the expression level of EZH2 in gliomas was significantly higher than that in normal brain tissues." (PMID 36527092, 2022). "Using transcriptomic data of LGG, GBM, and NT, we verified the previous evidence that EZH2 was overexpressed in glioma and correlated to the degree of tumor progression." (PMID 35197928, 2022). "These modifications protected the mRNA of EZH2 from nonsense-mediated mRNA decay), and EZH2 can increase TMZ resistance in gliomas." (PMID 36437944, 2022). "Initially, we verified previous data indicating that EZH2 expression is higher in gliomas than in NT, increasing with tumor progression." (PMID 35197928, 2022). "Our results support the utility of EZH2 expression as a potential predictor in the prognosis of glioma patients that functions through a variety of mechanisms to promote immune evasion and tumour progression." (PMID 33277782, 2021). "EZH2 forms a repressive chromatin structure which eventually participates in regulating the development as well as lineage propagation of stem cells and glioma progression." (PMID 34745848, 2021). "They indicated that the secretion of EZH2 was slightly irregular, with a low labeling index (LI) in Grade II gliomas, while its secretion became more regular as well as widespread with high LI in higher-grade gliomas." (PMID 34745848, 2021). "In renal papillary cell carcinoma, low-grade glioma and hepatocellular carcinoma, poor prognosis was significantly correlated with high expression of all three genes, EZH2, SUZ12, and EED." (PMID 34202528, 2021).
glioma (continued). "These are likely to be differentiation related genes, consistently with the known dysregulation of EZH2 and its regulatory networks in high grade gliomas that are characterized by abundance of dedifferentiated glioma stem cells." (PMID 34131149, 2021). "EZH2 was found to be a candidate cancer therapeutic target, with several studies suggesting its potential therapeutic benefits against glioma." (PMID 34739394, 2021). "HOTAIR can promote the formation of H3K27me3 through the EZH2 protein, silence the transcriptional expression of genes and promote the malignant progression of glioma." (PMID 34082742, 2021). "To examine the expression level of EZH2 in glioma cell lines, we performed qRT‐PCR and Western blotting." (PMID 33277782, 2021). "To further evaluate the prognostic ability of EZH2 expression in glioma, we performed receiver operating characteristic curve (ROC) analysis." (PMID 33277782, 2021). "EZH2 was more secreted in GBM than in low-grade gliomas as well as extremely secreted in U251 and U87 human glioma cells." (PMID 34745848, 2021). "In glioma, EZH2 was declared to be overexpressed in tumor tissues, and elevated EZH2 expression is closed related to the glioma grade and a bad prognosis." (PMID 34739394, 2021). "In summary, miR-1297 appeared to inhibit the invasive, migratory and proliferative capabilities of glioma cells through its action on EZH2." (PMID 33901010, 2021). "In this study, we sought to characterize the expression, biological function and regulatory mechanism of DLGAP1-AS1, miR-1297 and EZH2 in glioma." (PMID 33901010, 2021). "In this study, we verified that EZH2 is significantly up‐regulated in glioma tissues and cell lines." (PMID 33277782, 2021). "Previous study has also revealed the activated EZH2 in glioma stem cells promoted cellular survival under stress and was potential to serve as tumor therapeutic targets." (PMID 35059393, 2021). "EZH2 expression was detected in glioma cells transfected with sh-EZH2, miR-1297 mimics or miR-1297 mimics in combination with the EZH2 plasmid." (PMID 33901010, 2021). "Microarray studies of U87MG glioma cells after EZH2 silencing revealed a robust transcriptional reduction of the AXL receptor kinase." (PMID 34745848, 2021). "To determine how EZH2 contributes to glioma pathogenesis, we performed Gene Set Enrichment Analysis (GSEA) of tissues with different EZH2 expression levels." (PMID 33277782, 2021). "It was established that EZH2 was more secreted in GBM than in low-grade gliomas as well as extremely secreted in U87 human glioma cells." (PMID 34745848, 2021). "They indicated that miR-328 served as a tumor inhibitor by abolishing EZH2 activities on glucose metabolism in glioma cells." (PMID 34745848, 2021). "EZH2 was more secreted in glioblastoma multiforme than in low-grade gliomas as well as extremely secreted in U251 and U87 human glioma cells." (PMID 34745848, 2021). "Our results showed for the first time that curcumol is effective in inhibiting malignant biological behaviors and TMZ-resistance of glioma cells by suppressing FOXD2-As1-mediated EZH2 activation." (PMID 34739394, 2021). "Glioma progression appears to be supported DLGAP1-AS1 -promoted activation of the miR-1297/EZH2 axis." (PMID 33901010, 2021). "Search parameters were EZH2 and/or the posttranslational modifications, microenvironment, signaling pathways, biomarker, and therapy in gliomas." (PMID 34745848, 2021). "Ribavirin, another HCV antiviral, decreased glioma cell growth and migration in vitro by targeting the eukaryotic initiation factor, EZH2, and extracellular signal-regulated kinase (ERK) pathways." (PMID 33919596, 2021). "IHC staining verified EZH2 staining in glioma tissues and showed that EZH2 expression is grade‐dependent, with higher expression levels in GBM than in LGG." (PMID 33277782, 2021).
glioma (continued). "Whole genome sequencing showed the frequent incidence of histone H3 mutations in pediatric glioma patient samples and aberrant expression of EZH2 (enhancer of zeste homolog 2) and KDMs (lysine demethylases) in GBM patient samples." (PMID 34732244, 2021). "Accumulated evidence suggests that EZH2 is involved in tumorigenesis, affecting cell proliferation and apoptosis, epithelial to mesenchymal transition, invasion, and drug resistance in gliomas and other cancers." (PMID 33277782, 2021). "EZH2 was aberrantly secreted in glioma as well as contributed to the invasive and metastatic capabilities of GBM." (PMID 34745848, 2021). "EZH2 expression is significantly up‐regulated in the U87 and U251 glioma cells compared to HA‐1800 human astrocytes." (PMID 33277782, 2021). "EZH2 expression was significantly increased in glioma tissues vs normal tissues, with more obvious difference for GBM tissues than for LGG tissues." (PMID 33277782, 2021). "Cheng and Xu demonstrated that the blockade of EZH2 secretion expressively repressed proliferation as well as tumorigenic efficiency of glioma cells." (PMID 34745848, 2021). "The suppression of EZH2 gene secretion was capable of reversing temozolomide resistance in patients with glioma." (PMID 34745848, 2021). "First, EZH2 expression in sh-DLGAP1-AS1 transfected glioma cells (including sh-DLGAP1-AS1-1 and sh-DLGAP1-AS1-2) or sh-DLGAP1-AS1 together with miR-1297 inhibitors was explored using western blots and qRT-PCR." (PMID 33901010, 2021). "It was discovered that the glycolytic capability and reserve were both reduced when the concentrations of EZH2 are reduced in U87 as well as U251 glioma cells." (PMID 34745848, 2021). "Our results provide comprehensive understanding of the molecular mechanism of EZH2 in glioma, with potential relevance to prognosis and the development of novel therapies." (PMID 33277782, 2021). "HOTAIR regulated cell cycle progression in glioma cells via interactions with EZH2, and inhibition of HOTAIR repressed glioblastoma tumor growth in vivo." (PMID 34316694, 2021). "The expression level of EZH2 positively correlated with the malignancy of glioma and promoted the malignant behavior of glioma." (PMID 34178684, 2021). "GAS5 in glioma cells directly interacts with EZH2 (Enhancer of Zeste 2 Polycomb Repressive Complex 2 Subunit)." (PMID 34202777, 2021). "It was established that downstream of EZH2 had inhibitory effects on glioma growth via the blockade of the β-catenin signaling pathway." (PMID 34745848, 2021). "EZH2 possessed raised expressions in glioma tissues and cells in comparison to NHAs and normal brain tissues, as shown by qRT-PCR analysis." (PMID 33901010, 2021). "It was established that BMI1 and EZH2 secretion in glioma tissues were expressively elevated compared to those in nonneoplastic brain tissues." (PMID 34745848, 2021). "Studies are needed on the role of As3+ initiation of AKT-dependent pS21 EZH2 via the stimulation of the JNK-STAT3-AKT signaling axis in glioma." (PMID 34745848, 2021). "Our results verify that EZH2 displays obviously higher expression in glioma tissues than in adjacent normal tissues." (PMID 33277782, 2021). "To evaluate the prognostic value of EZH2 in glioma, we analysed gene expression data and corresponding clinicopathological information from the Chinese Glioma Genome Atlas, the Cancer Genome Atlas and GTEx." (PMID 33277782, 2021). "Further prospective experiments should be carried out to explore the molecular and immune mechanisms of EZH2 in glioma." (PMID 33277782, 2021). "The EZH2-mediated methyltransferase complex in the cytoplasm was capable of stimulating actin polymerization, cellular adhesion, and migration resulting in glioma dissemination." (PMID 34745848, 2021). "Our study highlights the oncogenic role of EZH2 in glioma progression which is in turn regulated by miR-1297." (PMID 33901010, 2021).
glioma (continued). "We used Cistrome Cancer to analyze data from The Cancer Genome atlas (TCGA) and showed that both in GBM as well as low grade gliomas (LGGs), patients with higher EZH2 expression have a worse prognosis in comparison to patients with lower EZH2 expression." (PMID 34336705, 2021). "Further, to study the PML-driven glioma growth and invasive properties, we employed DZNeP, an EZH2 methyl-transferase inhibitor." (PMID 34208139, 2021). "Previous studies revealed the upregulation of ENST00000545920, also known as lnc-SNHG1, in CRC, non-small-cell lung cancer, gastric cancer, and glioma to promote cancer cell growth by interacting with EZH2 in the nucleus and miR-154-5p in the cytoplasm." (PMID 34211553, 2021). "Inhibition of EZH2 expression has been shown to strongly impair glioma cell self‐renewal in vitro and tumour‐initiating capacity in vivo, and to improve drug and radiotherapy resistance." (PMID 33277782, 2021). "By inhibiting EZH2 to interfere with the Wnt/β-catenin pathway, the progression of glioma can be inhibited." (PMID 34335707, 2021). "They indicated that the knockdown of EZH2 suppressed glioma cell proliferation as well as invasiveness, and it also suppressed AXL receptor kinase secretion." (PMID 34745848, 2021). "Our decision to evaluate the predictive ability of EZH2 was based on recent studies suggesting that it is an oncogene in glioma." (PMID 33277782, 2021). "Additional, transwell, colony formation, and CCK-8 assays were performed and revealed that the impact of miR-1297 mimics on glioma cell invasion, migration and proliferation was reversed upon exposure to the EZH2 plasmid." (PMID 33901010, 2021). "In this regard, it has been shown that FAM83H‐AS1 epigenetically silenced CDKN1A by binding to EZH2 in glioma cells." (PMID 32839509, 2020). "Other evidence indicated that NEK2 promoted glioma stem cell radioresistance through the regulation of EZH2." (PMID 32503578, 2020). "It is reported in studies that the low expression of miR-101 in glioma cells can lead to the upregulation of EZH2, thereby enhancing the proliferation, invasion and migration of glioma cells." (PMID 31966062, 2020). "Accumulating evidences displayed the upregulation of EZH2 in glioma tissues and cells, which supported our results." (PMID 33363140, 2020). "Infection with Lenti-EZH2 in glioma cells significantly decreased the proportion of co-cultured M2 macrophages." (PMID 33363140, 2020). "In glioma harboring telomerase reverse transcriptase (TERT) promoter mutations, TERT and EZH2 cooperate in the activation of PGC-1α, which is involved in the expression of fatty acid synthase (FASN)." (PMID 32448308, 2020). "From RT-qPCR results, with the increase of glioma grade, the expression of IL-6 in glioma clinical samples showed a downward trend, while expression of EZH2, IL-8, and MIP-3α exhibited an upward trend." (PMID 33363140, 2020). "Hence, we speculated that EZH2 was associated with macrophage polarization in glioma." (PMID 33363140, 2020). "Meanwhile, immunofluorescence depicted that the expression of MIP-3α and IL-8 was strikingly declined but IL-6 expression was remarkably elevated in co-cultured M2 macrophages after infection with Lenti-EZH2 in glioma cells." (PMID 33363140, 2020). "It has been recently reported that EZH2 inhibition increases cell apoptosis and reduces cell proliferation in glioma, and it also potentially prevents macrophage-dependent disease development." (PMID 33363140, 2020). "Conclusively, we have confirmed that EZH2 serves as an oncogene in glioma by downregulating miR-454-3p." (PMID 33363140, 2020). "In the current study, we demonstrated that glioma patients expressed aberrant EZH2 and CXCR4 levels and that these levels were significantly associated with patient survival according to GEPIA." (PMID 32635336, 2020). "We also demonstrate that EZH2 promotes M2 macrophage polarization in glioma by increasing m6A modification of PTEN via inhibiting miR-454-3p." (PMID 33363140, 2020).
glioma (continued). "An existing study identified the ability of EZH2 to repress miR-708 expression by incorporating promoter methylation in the glioma tissues and cells." (PMID 33292225, 2020). "EGFR is a member of the Erb family of RTKs regulating EGFR/NEAT1/EZH2 axis, and is critical for glioma cell growth and invasion." (PMID 32001707, 2020). "H3K27M diffuse midline glioma cells lose EZH2-deposited H3K27me3 epigenetic transcriptional control markers, which are known to play crucial roles in cell differentiation and development in the brain." (PMID 33319914, 2020). "Taken together, EZH2 overexpression contributed to glioma development by inducing miR-454-3p DNA methylation and decreasing miR-454-3p expression." (PMID 33363140, 2020). "Expression of EZH2 was positively correlated with the degree of M2 macrophage polarization in glioma tissues." (PMID 33363140, 2020). "Initially, our results found that with the increase of glioma WHO grade, EZH2 expression in glioma clinical samples showed an increasing trend." (PMID 33363140, 2020). "At the molecular level, one report showed that MET/EGFR signaling is regulated by FAM83H-AS1, and16 showed that FAM83H‐AS1 epigenetically silenced CDKN1A by binding to EZH2 in glioma cells." (PMID 32839509, 2020). "LncRNA HOXB13-AS1 exacerbates glioma progression by regulating HOXB13 gene methylation through interacting with EZH2." (PMID 33109776, 2020). "For example, Circ-EZH2 promotes cell growth, migration and invasion but inhibits cell apoptosis through miR-1265 Sponge Activity in Glioma." (PMID 32460831, 2020). "EZH2, NFE2L2, REST, SMAD4 and SUZ12 were all implicated as common transcriptional regulators of DEGs in glioma, sarcoma, breast and stomach cancers, suggesting that altered AMPK signaling converged on similar groups of transcriptional targets." (PMID 32807122, 2020). "Collectively, EZH2 silencing decreased the growth of glioma and delayed M2 macrophage polarization in nude mice." (PMID 33363140, 2020). "EZH2 has been reported as an oncogene and is involved in several glioma cell processes, including cell cycle, invasion, GSC maintenance, drug and radiotherapy resistance, etc." (PMID 32373523, 2020). "Our subsequent experiments documented that EZH2 upregulation contributed to M2 macrophage polarization in glioma by downregulating PTEN through miR-454-3p-dependent promotion of PTEN, characterized by IL-6 downregulation and IL-8 and MIP-3α upregulation." (PMID 33363140, 2020). "EZH2 is involved in self-renewal of glioma stem-like cells, and its inhibition has been reported as a potential therapeutic strategy for pontine gliomas." (PMID 32604718, 2020). "Initially, the expression of CD206, a specific marker of M2 macrophages, and EZH2 level in different grades of clinical glioma samples were detected by immunohistochemistry." (PMID 33363140, 2020). "It is revealed that the glycolytic capacity and reserve are both diminished when the levels of EZH2 are decreased in U87 and U251 glioma cells." (PMID 32448308, 2020). "EZH2 was silenced by lentivirus in glioma cells, which were subsequently co-cultured with macrophages to evaluate its effect on macrophage polarization." (PMID 33363140, 2020). "Clinical samples of different grades of glioma and glioma cells were collected and immunohistochemistry and RT-qPCR demonstrated that EZH2 was highly expressed in glioma tissues." (PMID 33363140, 2020). "The results demonstrated that infection with Lenti-EZH2 in glioma cells appreciably reduced the expression of MIP-3α and IL-8 and increased the expression of IL-6 in co-cultured M2 macrophages." (PMID 33363140, 2020). "The expression of miR-133b and EZH2 in glioma cells was altered to examine their functions on cell activities." (PMID 31842978, 2019). "The expression profiles of MELK, EZH2 and NF-κB represent another prognostic factor for glioma patients, further supporting the clinical application in precise diagnosis and treatment." (PMID 31380279, 2019).